HTR6 (5-hydroxytryptamine receptor 6)
Description:
G protein-coupled receptor for 5-hydroxytryptamine (serotonin), a biogenic hormone that functions as a neurotransmitter, a hormone and a mitogen. Also has a high affinity for tricyclic psychotropic drugs (By similarity). Ligand binding causes a conformation change that triggers signaling via guanine nucleotide-binding proteins (G proteins) and modulates the activity of downstream effectors. HTR6 is coupled to G(s) G alpha proteins and mediates activation of adenylate cyclase activity. Controls pyramidal neurons migration during corticogenesis, through the regulation of CDK5 activity (By similarity). Is an activator of mTOR signaling.
Synonyms: 5-HT6; 5-HT6R
Tractability: Small molecule: an approved drug acts on it; a structure with a bound ligand is known; a high-quality ligand is known; it belongs to a druggable protein family. Antibody: UniProt places it where antibodies can reach, with high confidence; its Gene Ontology location is reachable by antibodies, with high confidence; UniProt predicts a signal peptide or a membrane-spanning region. PROTAC: a small molecule that binds it is known.
Target class: Monoamine receptor; Family A G protein-coupled receptor; Small molecule receptor (family A GPCR); Serotonin receptor; Membrane receptor
Safety:
Unwanted effects reported when the protein is acted on. In parentheses: how it was acted on, where the effect was seen, and who reports it.
reduced appetite (inhibition; central nervous system; source: Brennan et al. (2024))
weight loss (inhibition; central nervous system; source: Brennan et al. (2024))
weight gain (source: ClinPGx)
Gene: Protein-coding gene on chromosome 1 (19,664,875 to 19,680,966, forward strand). Ensembl gene ENSG00000158748.
Subcellular location: Cell membrane
Pathways (Reactome):
Signal Transduction: G alpha (s) signalling events; Serotonin receptors
Gene Ontology:
Molecular function: G protein-coupled serotonin receptor activity; protein binding; histamine receptor activity; neurotransmitter receptor activity; G protein-coupled receptor activity
Biological process: adenylate cyclase-activating serotonin receptor signaling pathway; positive regulation of TOR signaling; adenylate cyclase-modulating G protein-coupled receptor signaling pathway; cerebral cortex cell migration; chemical synaptic transmission; G protein-coupled receptor signaling pathway, coupled to cyclic nucleotide second messenger; G protein-coupled receptor signaling pathway; G protein-coupled serotonin receptor signaling pathway; positive regulation of cell communication; positive regulation of signaling
Cellular component: plasma membrane; dendrite; cilium; membrane; synapse
Genetic constraint (gnomAD): Loss-of-function variants: 16 observed, 17.19 expected, observed/expected ratio (o/e) 0.93, 90% interval 0.63 to 1.41. The upper end of that interval is the gene's LOEUF score, 1.41, which puts it in group 5 of 6, group 1 being the genes least tolerant of losing a copy. Missense variants: 578 observed, 617.05 expected, observed/expected ratio (o/e) 0.94, 90% interval 0.87 to 1. Synonymous variants: 326 observed, 299.15 expected, observed/expected ratio (o/e) 1.09, 90% interval 1 to 1.19.
Homologues: Orthologues: chimpanzee HTR6 (99% identical), macaque HTR6 (98% identical), mouse Htr6 (88% identical), guinea pig HTR6 (87% identical), zebrafish htr6 (54% identical), Drosophila melanogaster 5-HT7 (27% identical). Paralogues in human: HTR7 (27% identical), HTR2C (24% identical), HTR2A (24% identical), HTR2B (23% identical), HTR1B (23% identical), HTR1E (22% identical), HTR5A (22% identical), HTR1F (21% identical).
Diseases named in the same sentence as HTR6 in open-access papers:
HTR6 is named in the same sentence as 53 diseases in open-access papers, as found by Europe PMC text mining. Sharing a sentence is not in itself a finding about the gene and the disease. The quoted sentences say what the papers report.
Alzheimer disease (15 papers, 2014 to 2025). A progressive, neurodegenerative disease characterized by loss of function and death of nerve cells in several areas of the brain leading to loss of cognitive function such as memory and language. "The 5-hydroxytryptamine receptor 6 (5-HT6) has gained attention as a target for developing therapeutics for Alzheimer’s disease, schizophrenia, cognitive dysfunctions, anxiety, and depression, to list a few." (PMID 35890133, 2022). "Drugs targeting HTR6 hold promise for treatment of disorders such as anxiety, depression, eating disorders, schizophrenia, and Alzheimer’s disease, and as memory enhancers." (PMID 33372037, 2021). "HTR6 localizes to neuronal cilia and regulates their length, morphology and composition, effects through which it affects cognition in a mouse Alzheimer’s disease model." (PMID 33372037, 2021). "Serotonin receptor 6 (HTR6) and somatostatin receptor 3 (SSTR3) are two brain-enriched ciliary GPCRs involved in cognition and pathologies such as Alzheimer’s disease and cancer." (PMID 33372037, 2021).
schizophrenia (8 papers, 2020 to 2025). A major psychotic disorder characterized by abnormalities in the perception or expression of reality. "The present paper describes the results of an association study of in the end 24 polymorphic variants of HTR1A, HTR1B, HTR2A, HTR2C, HTR3A, HTR3B, and HTR6 genes with TD and two of its subtypes in 449 patients with schizophrenia." (PMID 32390801, 2020). "This study aimed to examine molecular associations of HTR1A, HTR1B, HTR2A, HTR2C and HTR6 gene polymorphisms with acute EPS in 229 male schizophrenia patients, following two weeks of haloperidol monotherapy." (PMID 32231051, 2020). "In addition to HTR1B, other 5-HT receptors, including HTR1A, HTR2A, HTR3, HTR4, and HTR6 are associated with schizophrenia." (PMID 37990254, 2023). "As some of the individual differences in the susceptibility to AIP might be due to the genetic background, this study aimed to examine the associations of SLC6A3, HTR2C and HTR6 gene polymorphisms with AIP in haloperidol-treated schizophrenia patients." (PMID 36551993, 2022). "Therefore, the haloperidol-treated schizophrenia patients were grouped according to the combined presence of HTR6 T and SLC6A3 9R alleles, which were identified as risk alleles for AIP." (PMID 36551993, 2022). "This study investigated the associations of HTR2C rs3813929 and rs518147, HTR6 rs1805054 and SLC6A3 3′UTR VNTR polymorphisms with haloperidol-induced parkinsonism, evaluated using the ESRS, in 229 male patients with schizophrenia." (PMID 36551993, 2022). "We have investigated the associations of individual SLC6A3, HTR2C and HTR6 gene polymorphisms; HTR2C haplotypes; as well as the combination of HTR6 and SLC6A3 risk alleles with haloperidol-induced parkinsonism in schizophrenia patients." (PMID 36551993, 2022). "A set of 29 SNPs of genes of serotonin receptors HTR1A, HTR1B, HTR2A, HTR2C, HTR3A, HTR3B, and HTR6 was studied in a population of 449 Caucasians (226 females and 223 males) with verified clinical diagnosis of schizophrenia (according to ICD-10: F20)." (PMID 32390801, 2020). "Therefore, further studies should be conducted to test a wider range of antipsychotics and other drugs for the association of the SLC6A3, HTR2C and HTR6 polymorphisms, as well as CYP2D6 gene variants with AIP, in both male and female schizophrenia patients of different ethnicities." (PMID 36551993, 2022).
Anxiety (6 papers, 2014 to 2025). Intense feelings of nervousness, tension, or panic often arise in response to interpersonal stresses. "Serotonin receptor 5-hydroxytryptamine receptor 6 (HTR6) has been shown to regulate neuronal migration and differentiation during development and is also implicated in mental disorders, such as anxiety and depression." (PMID 30883547, 2019).
depression (6 papers, 2014 to 2025). "Focusing on the serotonergic system—the foundation of the monoamine hypothesis of depression—we observed a significant reduction in 5-HT levels in the PFC following FMT, along with H3K27me3-mediated transcriptional repression of key genes including Tph2, Htr1d, Htr2a, Htr3a, Htr6, and Htr7." (PMID 41041075, 2025).
bipolar disorder (3 papers, 2022 to 2025). A disorder of the brain that causes unusual shifts in mood, energy, activity levels and the ability to carry out day-to-day tasks. "An example of one such gene is HTR6, a serotonin receptor targeted by certain antidepressant and antipsychotic medication and found to be strongly associated and colocalized with BP in the most recent Psychiatric Genomics Consortium (PGC) study on bipolar disorder." (PMID 38306997, 2024).
breast carcinoma (3 papers, 2022 to 2024). "The genetic alteration of HTR1D, HTR3A, HTR3B, and HTR6 in breast cancer patients was significantly associated with shorter overall survival (OS)." (PMID 37795441, 2023). "These authors also noted that HTR6 expression in high-grade breast cancer was lower than that in less invasive cancers, which requires further studies considering our results." (PMID 39267843, 2024). "Taken together, we revealed a new function of neurotransmitter receptors in breast cancer and identified HTR6 as a survival-related gene potentially regulating the immune microenvironment." (PMID 35359970, 2022). "Among all these receptors, we revealed decreased expression of HTR6 in human advanced breast cancer versus tumors in situ using our original data (n = 44)." (PMID 35359970, 2022). "As a result, the phosphorylation of 294 genes was correlated with HTR6 expression in breast cancer (correlation coefficient > 0.3 or < -0.3)." (PMID 35359970, 2022). "The results showed that HTR6 was universally expressed in benign tumors, thyroid cancer, breast cancer, and other nine human tumors." (PMID 35359970, 2022). "Next, we explored the function of HTR6 in different subtypes of breast cancer by analyzing its influence on patient survival." (PMID 35359970, 2022). "Subsequently, we analyzed the RFS of different subtypes of breast cancer responding to HTR6 expression." (PMID 35359970, 2022). "To verify the expression of HTR6 in breast cancer and explore its functions in tumor progression, we detected HTR6 protein in breast cancer tissues from 44 patients using an immunohistochemical assay." (PMID 35359970, 2022). "Subsequently, to confirm HTR6 expression regulating immune infiltration and then affecting the development of breast cancer, we examined the correlation between HTR6 mRNA expression and RFS of breast cancer patients with high or low immune infiltration." (PMID 35359970, 2022). "Since HTR6 was down-regulated in invasive breast cancer and metastases versus tumor in situ, this result suggested that FOXA1 might be the negatively regulatory TF of HTR6 in breast cancer." (PMID 35359970, 2022). "Finally, we depicted the pathways that HTR6 participated in and revealed the reasons for the altered expression of HTR6 in breast cancer using multi-omics analyses." (PMID 35359970, 2022). "Therefore, we explored the role of HTR6 in the immune microenvironment of breast cancer." (PMID 35359970, 2022). "We analyzed the biological processes and pathways that HTR6 might regulate in breast cancer." (PMID 35359970, 2022). "Finally, we uncovered two possible reasons for HTR6 down-regulation in breast cancer, including deep deletion in the genome and the up-regulation of FOXA1 in breast cancer, which was a potential negatively regulatory transcription factor of HTR6." (PMID 35359970, 2022). "As a result, HTR6 expression was associated with the RFS of Luminal A and Luminal B breast cancer, but not Basal-like." (PMID 35359970, 2022). "This suggested that FOXA1 might be one negative TF for HTR6 in breast cancer." (PMID 35359970, 2022).
Parkinson disease (3 papers, 2019 to 2023). A progressive degenerative disorder of the central nervous system characterized by loss of dopamine producing neurons in the substantia nigra and the presence of Lewy bodies in the substantia nigra and locus coeruleus. "Nominally significant associations of the HTR6 rs1805054 genotype with ESRS subscale II for parkinsonism (H = 6.06, p = 0.048) and ESRS-based rigidity (H = 6.90; p = 0.032) scores were rejected due to the Bonferroni correction." (PMID 36551993, 2022). "When investigating whether the ESRS-based parkinsonism indicators were different in carriers of particular HTR6 rs1805054 alleles, we observed several nominally significant associations with the scores on different ESRS subscales and items for AIP." (PMID 36551993, 2022). "Therefore, future studies should analyze the possible interaction between CYP2D6 gene variants and the variants of the SLC6A3, HTR2C and HTR6 genes on the risk for haloperidol-induced parkinsonism." (PMID 36551993, 2022). "However, to the best of our knowledge, this is the first work that shows that the combination of HTR6 and SLC6A3 risk alleles is associated with the development of haloperidol-induced parkinsonism." (PMID 36551993, 2022). "Additionally, the findings indicated a combined effect of HTR6 T and SLC6A3 9R alleles on AIP, with their combination associated with significantly lower scores of ESRS subscale II for parkinsonism, ESRS-based tremor or hyperkinesia and ESRS subscales VI and VIII." (PMID 36551993, 2022). "In addition, we also detected a possible combined effect of HTR6 T and SLC6A3 9R alleles on AIP, with their particular combination associated with significantly lower scores of ESRS subscale II for parkinsonism, ESRS-based tremor or hyperkinesia and ESRS subscales VI and VIII." (PMID 36551993, 2022).
psychosis (3 papers, 2014 to 2021). "Among them, the serotonin (5-HT) receptor (HTR6), a G protein coupled receptor with high affinity for Meth, biomarker of mood disorders, and Meth-induced psychosis, and with relevance in Meth-associated behaviors was 2.2-fold increased by Meth-induced sensitization (FDR_BH p = 0.02)." (PMID 32283831, 2020).
endometrial carcinoma (2 papers, 2022 to 2025). A malignant tumor arising from the epithelium that lines the cavity of the uterine body. "They found that HTR6 and GRIN1 regulated endometrial carcinoma cell migration and the EMT process." (PMID 40661182, 2025).
in situ breast cancer (2 papers, 2022 to 2024). "We found that the expression of HTR6 in invasive breast cancer, lymph node metastases, and distal metastases was lower than that in situ breast cancer." (PMID 35359970, 2022).
Crohn disease (1 paper, 2016). A gastrointestinal disorder characterized by chronic inflammation involving all layers of the intestinal wall, noncaseating granulomas affecting the intestinal wall and regional lymph nodes, and transmural fibrosis. "Examples of this sharing of eQTLs between related cell types include a myeloid-specific eQTL for KSR1 (at a GWAS locus for Crohn’s disease) and T cell-specific eQTLs for DEPTOR and HTR6." (PMID 27015630, 2016).
prostate carcinoma (1 paper, 2024). A carcinoma that arises from epithelial cells of the prostate gland. "Among these, HTR2A and HTR2B were positively associated with lethal prostate cancer, while HTR6 was inversely associated." (PMID 38995644, 2024).
Tremor (1 paper, 2022). An unintentional, oscillating to-and-fro muscle movement about a joint axis. "In contrast to our previous findings, present data revealed significant association between HTR6 rs1805054 polymorphism and haloperidol-induced tremor and rigidity." (PMID 36551993, 2022). "The results revealed significant associations between HTR6 rs1805054 polymorphism and haloperidol-induced tremor and rigidity." (PMID 36551993, 2022).
cancer (7 papers, 2021 to 2025). A tumor composed of atypical neoplastic, often pleomorphic cells that invade other tissues. "One of the last mRNAs that differentiated cancer samples independent of subtype from control samples, for which a decrease in transcriptional activity was demonstrated in cancer tissues, was HTR6." (PMID 39267843, 2024). "After a pan-cancer analysis including 22 cancers (n = 11262), we disclosed that HTR6 was expressed in 12 tumors and uncovered its influence on survival in seven tumors." (PMID 35359970, 2022). "Combined with our results and previous reports, we suspect that HTR6 and GRIN1 play important roles in cancer development and warrant further investigation." (PMID 40661182, 2025).
neurological diseases (4 papers, 2016 to 2022). "The alteration in mRNA levels of Htr2a, Htr4, Htr7, Htr5b, Htr6, and Htr3 indicate that serotonin may increase the risk of CJL mediated neurological disorders." (PMID 36582489, 2022).
tumor (3 papers, 2022 to 2024). "KEGG enrichment analysis of the HTR6 co-expressed phosphorylations revealed that HTR6 might regulate the MAPK pathway and tumor-related pathway." (PMID 35359970, 2022).
HTR6 also shares sentences with these, for which no sentence is quoted: cognitive deficits (17 papers); psychiatric disorder (5); Obesity (4); dementia (3); glioma (3); memory impairment (3); astrocytoma (2); breast adenocarcinoma (2); cognitive decline (2); cognitive disorder (2); epilepsy (2); invasive breast carcinoma (2); neuroblastoma (2); neurodegenerative disease (2); age (1); benign tumors (1); brain disorder (1); Cerebral ischemia (1); cholangiocarcinoma (1); ciliopathies (1); colon cancer (1); diseases of the central nervous system (1); Dyskinesia (1); eating disorder (1); esophageal adenocarcinoma (1); glioblastoma (1); head and neck squamous cell carcinoma (1); hepatocellular carcinoma (1); hyperkinesia (1); lung carcinoma (1).
A further 7 diseases each share a sentence with HTR6 in 1 paper.